MAP3K14 (mitogen-activated protein kinase kinase kinase 14)
Diseases named in the same sentence as MAP3K14 in open-access papers (continued):
Sharing a sentence is not in itself a finding about the gene and the disease.
tumor (16 papers, 2015 to 2024). "We analyzed the role of MAP3K14 in HCC using the UALCAN database and found that MAP3K14 is closely associated with individual cancer stage, tumor grade, and age in HCC." (PMID 38577603, 2024). "Furthermore, TRAF2, BIRC3 and MAP3K14 were recurrently mutated in approximately 17% of a cohort of 165 MCL tumor tissues investigated by genomic profiling." (PMID 33413657, 2021). "First, we verified the high expression of MAP3K14 in tumor tissues and poor prognosis in TCGA and GEO cohorts and immunohistochemistry." (PMID 38577603, 2024). "The mRNA and protein expression levels of MAP3K14 in tumor tissues were higher than those in normal tissues (p < 0.05)." (PMID 38577603, 2024). "The expression of MAP3K14 was correlated with Pathologic T stage (p=0.026), Pathologic stage (p=0.032), Tumor status (p=0.024) and AFP (p=0.002)." (PMID 38577603, 2024). "To validate our results at the protein level, we performed IHC staining to detect the expression of MAP3K14 in 180 HCC tissue samples (including 94 tumor samples and 86 normal tissue samples)." (PMID 38577603, 2024). "Firstly, the expression levels of MAP3K14 in different tumor tissues and adjacent tissues were examined using the Timer database." (PMID 38577603, 2024). "Tumor pathologic grade has important prognostic significance and patients with high-grade tumors tended to exhibit higher MAP3K14 mRNA levels." (PMID 38577603, 2024). "Generally, the methylation level in the promoter region is negatively correlated with gene expression, which partially explains the upregulation of MAP3K14 in tumor tissues." (PMID 38577603, 2024). "According to reports, MAP3K14 is considered an oncogene and is aberrantly expressed in various types of tumor cells." (PMID 38577603, 2024). "LCMV-induced tumour regression was dependent on Map3k14, suggesting that immune infiltration is crucial." (PMID 28248314, 2017). "This implies that MAP3K14 may influence the interaction between immune cells and malignant tumor cells, thereby regulating the progression of HCC." (PMID 38577603, 2024). "The genomic profiling of archived MCL tumor samples has identified recurrent mutations in the TRAF2, BIRC3, and MAP3K14 genes, suggesting a dependence on either the BCR-BTK-NF-κB (classical) or MAP3K14-NF-κB (alternative) pathways for MCL pathogenesis." (PMID 38542207, 2024). "Compared with normal tissues, MAP3K14 mRNA expression was upregulated in tumor tissues (P<0.05)." (PMID 36119471, 2022). "A translocation bringing the IGH loci in proximity to MAP3K14 was gained at relapse in one tumour." (PMID 33057009, 2020). "Notably, a point mutation in MAP3K14 was identified in a MCL sample (P13-P), which further suggests that genetic characterization of the tumor genome will be important for the choice of therapeutic strategy for MCL patients." (PMID 27224912, 2016). "The interaction between BIRC3, MAP3K14, and the NF-κB pathway highlights the impact of BIRC3 inactivation on tumor cells dependent on this pathway." (PMID 39301019, 2024). "UALCAN was used to assess the relationship between MAP3K14 expression and the clinicopathologic features of HCC patients, including cancer stage, tumor grade and patient age." (PMID 38577603, 2024). "The intratumoral heterogeneity was also explored using the Tumor Purity value, with which CXCL11, ERAP2, FYN, GH1, MAP3K14, and SEMA6C were found negatively correlated, while the rest were positively correlated." (PMID 36428747, 2022). "We further validated the expression of MAP3K14 using the UALCAN database and GEO datasets of paired HCC samples, which showed significantly higher expression levels of MAP3K14 in tumor tissues compared to adjacent non-tumor tissues." (PMID 38577603, 2024). "Upon binding, various kinases, including PI3K, and MAP3K14, and several transcription factors such as nuclear factor-kappa B (NF-kB), AP-1 and Ets-1 are activated leading to OPN-induced tumor growth, angiogenesis, tumor metastasis and inhibition of apoptosis." (PMID 25749383, 2015).
tumor (continued). "In contrast, PD-PDX kinases with potential to be restored by the addition of MSCs include ACVR1C (ALK7), MAP3K14 and ROR1, which may be inhibitors of tumour growth, and JAK1, involved in the STAT3 signalling pathway characteristic of the inflammatory molecular subclass of CCA." (PMID 39492622, 2024). "Here, we show that NF-κB-inducing kinase (NIK/MAP3K14), a critical upstream regulator of the noncanonical NF-κB pathway, is both necessary and sufficient for cell-intrinsic invasion, as well as invasion induced by the cytokine TWEAK, which is strongly associated with tumor pathogenicity." (PMID 27270613, 2016). "MAP3K14 (NIK1), BIRC2 (cIAP1), RIPK1, CASP7, CASP8, and TNF play an important role in inhibiting proliferation and invasion of tumor cells via the activation of the non-canonical NF-κB signaling pathway." (PMID 34638912, 2021). "Due to the relationship between BIRC3, MAP3K14 and the non-canonical NF-kB pathway, BIRC3 inactivation bears consequences also on the tumor cells relying on NF-kB pathway to survive." (PMID 33413657, 2021).
cancer (11 papers, 2015 to 2025). A tumor composed of atypical neoplastic, often pleomorphic cells that invade other tissues. "Examples of potentially anti-proliferative pathways activated by paracrine signalling include those involving ACVR1C, MAP3K14 and ROR1, linked to inhibition of cancer growth including in the context of CCA." (PMID 39492622, 2024). "In this study, we first analyzed the pan-cancer expression of MAP3K14 using the TIMER2.0 database and found that MAP3K14 is highly expressed in various cancers, including HCC." (PMID 38577603, 2024). "After NMI knockdown, the expression levels of MAPK signaling pathway members, including Raf1, MAPK11, MAP3K14 and MAP3K2, which are associated with cancer invasion and metastasis, were obviously decreased HCC-LM3." (PMID 28077802, 2017). "MAP3K14 is highly expressed in various malignant tumors, including HCC." (PMID 38577603, 2024). "This might be due to mutations in MAP3K14/NIK or MAP3K1/MEKK1 of TE617.T cells, which result in an alternative splice variant or a threonine deletion at position 949, respectively (The Cancer Cell Line Encyclopedia)." (PMID 34172934, 2021). "It was shown that MAP3K14, PTN, ACVR1 and HCK sharing different DNA methylation and gene expression across cancers were relatively high degree distribution in PPI network." (PMID 25774687, 2015).
immune disorder (2 papers, 2021 to 2025). "Our findings indicate that HSCT alone is insufficient to fully correct the immune disorder in MAP3K14 deficiency, likely due to non-hematopoietic defects in lymph node stromal structures and thymic central tolerance." (PMID 41280889, 2025).
infection (1 paper, 2020). The state of being infected such as from the introduction of a foreign agent such as serum, vaccine, antigenic substance or organism. "We systemically infected wild-type (WT) and Map3k14aly/aly mice with the acute strain of LCMV and analyzed viral replication early during the course of infection to validate our GWAS screening results concerning the relevance of Map3k14 for LCMV infection." (PMID 32033109, 2020).
kidney disease (1 paper, 2024). "Additionally, members of the MAP3K family, such as MAP3K5 (ASK1) and MAP3K14 (NIK), are known to be important in kidney disease, suggesting that modulating MAP3K11 activity could be a promising therapeutic strategy." (PMID 38892221, 2024).
MAP3K14 also shares sentences with these, for which no sentence is quoted: B-cell lymphoma (2 papers); ovarian carcinoma (2); pancreatic cancer (2); renal cell carcinoma (2); acute myeloid leukemia (1); adenocarcinoma of the rectum (1); asthma (1); atrial fibrillation (1); autoimmune disease (1); classical Hodgkin lymphoma (1); colon adenocarcinoma (1); coronary artery disease (1); cutaneous melanoma (1); dermatitis (1); eczema (1); eosinophilic esophagitis (1); epilepsy (1); Ewing sarcoma (1); head and neck squamous cell carcinoma (1); hypothyroidism (1); invasive breast carcinoma (1); MALT lymphoma (1); metabolic dysfunction-associated steatohepatitis (1); multiple myeloma (1); nephrotic syndrome (1); neuroblastoma (1); osteoarthritis (1); papillary thyroid cancer (1); Parkinson disease (1); rhabdomyosarcoma (1).
A further 5 diseases each share a sentence with MAP3K14 in 1 paper.